AFP (alpha fetoprotein)
Diseases named in the same sentence as AFP in open-access papers (continued):
Sharing a sentence is not in itself a finding about the gene and the disease.
tumor (continued). "The AFP response to therapy, as a result of this policy, would provide a more precise measurement of tumor biology over time as compared to the initial fears of recurrence from the static initial AFP value of 1000 ng/mL, as previously discussed." (PMID 36290870, 2022). "CTCs are increased in patients with HCC, and their levels correlate with the prolongation of the disease, tumor stage, and AFP serum levels." (PMID 36230554, 2022). "In the combination of training and validation groups, AFP level, tumor maximum diameter, and the number of nodules were significantly associated with MVI." (PMID 35875110, 2022). "Among cancer-related factors: poor differentiation, microvascular invasion, advanced TNM or BCLC stage and multiple HCCs, tumor size and increased alpha-fetoprotein blood levels." (PMID 36568174, 2022). "In the training cohort, patients with high ACLR (> 80) tended to have tumors with advanced clinical phenotypes including larger tumor size (P < 0.001), higher Edmondson’s grade (P < 0.001), more vascular invasion (P < 0.001), and higher AFP level (P = 0.004)." (PMID 35756674, 2022). "Tumor-related glycoprotein or glycan antigen alterations approved by the Food and Drug Administration (FDA), such as core fucosylated AFP (AFP-L3), are better targets for tumor diagnosis and prognosis than AFP alone." (PMID 35814473, 2022). "The proliferation subtype is characterized by high tumor grade (poor cell differentiation), high alpha-fetoprotein (AFP) levels, poor clinical outcomes, and dismal prognosis." (PMID 36292980, 2022). "In univariable analysis, tumor number, NLR, early AFP and DCP response and early tumor response (CR+PR vs. SD+PD) were significantly associated with PFS." (PMID 35860582, 2022). "With transcriptional targeting, CpGf-AFP-sr39 NPs resulted in highly targeted sr39 expression in the tumor alone." (PMID 35857843, 2022). "As a proof of concept, when using a tumor biomarker (AFP) as the analyte, the anti-AFP antibody was covalently immobilized onto the external surface of VMSF/ITO to produce the highly specific sensing interface." (PMID 36419588, 2022). "Overall, lower cost, simplicity of the test, and fewer traumatic inflammatory markers showed excellent predictive ability when combined with AFP, tumour diameter, MVI, PVTT, etc." (PMID 35255845, 2022). "Patients with HCC recurrence had larger maximal tumour size and a greater tumour count, higher AFP concentration, poorer TNM stage (p = .001), and higher prevalence of vascular invasion (p < .001) than those with non-recurrence." (PMID 35930293, 2022). "In this model, the upper limit of tumor burden at presentation revealed an inverse relation with the initial AFP level." (PMID 35529597, 2022). "combined AST, AFP, tumor margins, growth pattern, envelope, peritumor enhancement, and radiomics score to create a nomogram with AUC values of 0.909 and 0.889 in the training and validation cohorts, respectively." (PMID 35392229, 2022). "At present, α-fetoprotein (AFP) is the serum tumor marker most commonly used for surveillance and early diagnosis of HCC." (PMID 35193513, 2022). "On this basis, a combination of CEUS and tumor markers was carried out (simultaneous elevation of AFP and CA19-9 or elevated tumor markers in discordance with the imaging findings)." (PMID 35242699, 2022). "A commonly used tumor marker for HCC is alpha-fetoprotein (AFP), especially when it is significantly elevated, high vigilance should be exercised." (PMID 36591447, 2022). "AFP-L3 is a glycoform of AFP with a high affinity for Lens culinaris agglutinin, and it has shown promises for early detection and prediction of tumor aggressiveness in patients with HCC." (PMID 36161213, 2022). "CLIP is one of the most commonly used staging systems, combining liver function (Child–Pugh score) with tumor-related characteristics (tumor size and morphology, portal vein tumor thrombus, AFP)." (PMID 35810271, 2022).
tumor (continued). "As expected, DENA/2-AAF treatment also increased serum levels of the tumor markers AFP and CA19.9, in accord with previous studies." (PMID 35453384, 2022). "SSRP1 can regulate the proliferation and metastasis of HCC, its aberrant overexpression is related to higher serum AFP level, larger tumor size, and higher T stage of HCC patients." (PMID 35646665, 2022). "Of those where serum tumour markers were reported, AFP and bHCG were elevated prior to chemotherapy in at least 68% and 63% of patients, respectively." (PMID 36059636, 2022). "As a sensitive tumor marker for YSTs, serum AFP was measured every course to evaluate tumor response." (PMID 36452350, 2022). "For HCC patients with high AFP levels, an early AFP response is a noninvasive and practical alternative endpoint to assess the long-term tumor prognosis of patients." (PMID 36686731, 2022). "The possible reasons for this are associated with the cut-off value of AFP, stage of HCC, and tumor size." (PMID 35365115, 2022). "The serum AFP is the most widely used tumor biomarker currently in HCC patients even though the specificity of AFP is low." (PMID 35157721, 2022). "The multivariate analysis revealed better OS in female patients, patients with better ECOG PS, lower Child–Pugh class, lower mUICC stage, well-defined tumor, and lower AFP." (PMID 35324973, 2022). "Ultimately, the 5-5-500 criteria (tumor ≤ 5 cm in diameter, tumor number ≤ 5, and AFP ≤ 500 ng/mL) were established, with a 5-year recurrence rate of 7.3% (with a 95% confidence interval at 5.2–9.3) and a 5-year survival rate over 70%." (PMID 35053580, 2022). "The MobileNetV2_HCC_class was a strong predictor of RFS in the whole LT set and was even capable of stratification for other common prognostic features (Stage AJCC, AFP, tumor number, and tumor size)." (PMID 35352293, 2022). "Compared to the AFP-positive group, the patients in the AFP-negative group were older and had lower values of laboratory parameters, lower tumor aggressiveness, and less malignant MR imaging features." (PMID 35626229, 2022). "CSS, alpha-fetoprotein level, tumor size, tumor number, and macrovascular invasion were identified as independent predictors of both RFS and OS." (PMID 35637856, 2022). "In the pre-MORAL, the 3 preoperative independent predictors of worse survival were NLR ≥5, AFP >200, and tumor size >3 cm." (PMID 36268362, 2022). "In HCC patients, increased CENPA mRNA was associated with elevated alpha-fetoprotein, advanced TNM stage, larger tumor size, advanced AJCC stage, and advanced pathology grade." (PMID 36213834, 2022). "Of clinical relevance, in adults, AFP is mainly found in tumor cells of the liver, testes, and ovaries." (PMID 36518320, 2022). "The most commonly used predictors were AFP (n = 9), albumin (n = 8), bilirubin (n = 8), Child–Pugh class (n = 8), extrahepatic metastasis (n = 7), tumor size (n = 7), and vascular invasion (n = 6)." (PMID 35810271, 2022). "Evidence from the literature showed that tumour markers, such as AFP, B-hCG, CA125, CA19.9 and LDH, can be confusing." (PMID 36291507, 2022). "When tumors were measured at the end of the study, animals treated with CpGf-AFP-sr39 NPs had an average tumor area of 27 ± 4 mm2 compared with 71 ± 8 mm2 and 79 ± 16 mm2 for fLuc NP– and CpGf-CMV-sr39–treated animals, respectively." (PMID 35857843, 2022). "Compared with younger patients, elderly patients with HCC normally have lower AFP levels, lower rates of HBsAg positivity, and a lower tumor burden." (PMID 35715787, 2022). "In the current study, AFP level, Child-Pugh class, maximum tumour diameter, metastasis, and BCLC stage were demonstrated to predict OS in HCC patients treated with TACE, which were similar to previously reported data." (PMID 35639492, 2022). "Tumor markers, such as CA-125, alpha-fetoprotein, beta-human chorionic gonadotropin, and lactate dehydrogenase, are of limited use because of their substantial alteration by pregnancy." (PMID 36012938, 2022).
tumor (continued). "Nonetheless, CpGf-AFP-sr39 showed impressive therapeutic efficacy in vivo, with a 62% reduction in tumor size compared with controls." (PMID 35857843, 2022). "All patients had alpha-fetoprotein levels over 100 ng/ml, with values largely varying, in accordance with the tumour dimensions." (PMID 35497085, 2022). "On the basis of significant survival predictors including tumor size, tumor number, and AFP, we performed subgroup analysis in patients with different MVI grades." (PMID 35814378, 2022). "Other than tumor size and number, there was a significant difference in median AFP level (P = 0.01) and microvascular invasion (P = 0.001)." (PMID 34117916, 2022). "Our team developed a novel scoring system based on gender, tumor number, AFP, Fib, and albumin-to-prealbumin ratio to stratify patients with HCC into groups with different recurrence risks." (PMID 36389724, 2022). "Univariate analysis revealed that OS was correlated with treatment options (P = 0.025), maximum tumor diameter <10 cm (P = 0.017), and alpha-fetoprotein <400 (P = 0.015)." (PMID 35814420, 2022). "Male sex, ALT (>40 U/L), AFP (≥400 ng/mL), tumor size (cm), MVI, ALBI grade, and mALBI grade were significantly associated factors of survival in the univariate Cox regression analysis." (PMID 36291867, 2022). "Univariate analysis of factors involved in recurrence-free survival in 112 cases after PSM showed that the following were significant: treatment with DAAs (p = 0.0032), presence of a single tumor (p = 0.0030), and AFP levels of 10 ng/mL or lower (p = 0.0304)." (PMID 35565424, 2022). "In HCC, AFP was not only known to be a product of tumor but also contributes to tumor aggression as well as regulation of hepatocellular growth and tumorigenesis." (PMID 35847953, 2022). "Some of the tumor markers were recorded, such as AFP 5.90 (2.85–122.45) μg/L, CA19-9 8.75 (3.92–17.15) U/ml, CA125 14.35 (9.47–30.93) U/ml, and CA153, 8.70 (6.65–11.93) U/ml." (PMID 35794982, 2022). "The AFP presented high serum levels at postoperative follow-up in only 4 cases, and all of them had tumor recurrence." (PMID 36074393, 2022). "The results showed that positive CTC, the level of AFP ≥ 400 μg/L, and tumor number were independent predictors of MVI in both the training and validation cohorts (P < 0.05)." (PMID 35795230, 2022). "These risk factors, including AFP ≥ 400 kU/L (OR 0.276, P = 0.003), TBIL ≥ 34 mmol/L (OR 0.422, P = 0.015), tumor diameter (TD) ≥ 5 cm (OR 0.423, P = 0.022), and TNM stage (OR 0.238, P < 0.001), were screened by univariate logistic regression analysis." (PMID 36180867, 2022). "The MVI prediction model, based on preoperative AFP, tumor diameter, and TNM stage, presented superior predictive efficacy (AUC = 0.7997) and good practicability (high H-L goodness of fit, P = 0.231)." (PMID 36180867, 2022). "By univariate and multivariate regression analysis, tumor max diameter [HR = 1.795 (1.152–2.798)], AFP [HR = 1.955 (1.294–2.955)], ALP [HR = 2.584 (1.488–4.486)], and different treatment modalities were prognostic factors for BCLC stage 0/A rHCC patients." (PMID 35656507, 2022). "Although AFP has been widely used as a serum biomarker of tumor response for HCC, one of its significant limitations is that approximately 30-50% of patients with HCC are AFP “non-secretors”." (PMID 36263214, 2022). "Waterfall plots were plotted to compare the change in serum AFP levels as a tumor marker from baseline to the last follow-up." (PMID 36389724, 2022). "Previous studies identified some variables, AFP, DCP, ALP, tumor size, and tumor number, as independent risk factors for the recurrence of cHCC." (PMID 35227269, 2022). "The study also identified lower OGA expression as an independent predictor for HCC tumor recurrence after LT, especially in patients with low alpha fetoprotein (AFP) expression." (PMID 36104770, 2022).
tumor (continued). "The expression of PITX2 is associated with tumor size and overall survival rate, whereas only PITX2C expression is associated with AFP and differentiation in clinical patients." (PMID 35765089, 2022). "An elevated RAE1 expression level was correlated with a higher T stage, pathologic stage, tumor status, histologic grade, and AFP level." (PMID 35751040, 2022). "In this regard, pretransplant AFP, representative for biochemical tumor burden, was shown to correlate well with posttransplant recurrence." (PMID 35681642, 2022). "Alpha-fetoprotein is the most commonly used tumor marker for HCC, as it is able to predict disease prognosis and aids in monitoring tumor recurrence." (PMID 35884412, 2022). "The analysis of clinicopathologic characteristics in 154 HCC patients revealed that high SNRPD1 protein expression was significantly correlated to TNM staging, serum AFP level, tumor differentiation, vascular invasion, recurrence, and survival." (PMID 34976182, 2022). "Third, compared to patients who did not join the follow-up study, patients who were followed up had a higher proportion of HBV positivity, high AFP (≥20ng/ml), poor liver function, multiple tumor nodules, incomplete tumor capsules, and late BCLC stage." (PMID 35800051, 2022). "The serum tumor markers alpha-fetoprotein (AFP) and protein induced by vitamin K absence or antagonist-II (PIVKA-II) were markedly elevated (AFP: 3367 ng/mL, PIVKA-II: 885 mAU/mL)." (PMID 35659738, 2022). "Among the patients treated with lenvatinib, in the univariate analysis, intrahepatic tumor volume (<50% vs. ≥50%: HR 44.1; 95% CI 3.77–515; p = .0025), and AFP(<400 vs. ≥400: HR 2.95; 95% CI 1.16–7.51; p = .023) were associated with PFS." (PMID 35302279, 2022). "Since 2012, patients within UCSF criteria and those outside UCSF criteria (maximum tumor size ≤ 10 cm, any tumor number) with AFP < 1000 ng/ml were offered LDLT." (PMID 34117916, 2022). "In a word, this study showed a good performance of tumor size, AFP, and inflammatory markers in predicting MVI." (PMID 35310437, 2022). "The most commonly used predictors for developing prognostic models were AFP, albumin, bilirubin, Child–Pugh class, liver metastasis, tumor size, and vascular invasion." (PMID 35810271, 2022). "A higher AFP concentration is closely correlated with a poorer prognosis, higher aggressiveness of the tumor, and lower response to therapies." (PMID 35626229, 2022). "The analyses showed that the method reduced AFP by 9% (from 9.23 to 8.44) for 90% tumor-detection sensitivity by utilizing 1247 unlabeled T1c exams." (PMID 36010373, 2022). "The tumor markers measured at the time of referral were AFP (median: 15.3; interquartile range: 19.4; range: 1.3–831.4; reference range: 8.1 ng/mL) and PIVKA-II (median: 30.5; interquartile range: 72.5; range: 9–1353; reference range: 40 mAU/mL)." (PMID 35085305, 2022). "AFP-L3 which is considered as a new generation of tumor marker is usually referred to as AFP heteroplasmy and binds to lentinan." (PMID 35948592, 2022). "Male ratio, leukocyte count, hemoglobin level, albumin level, ALBI grade, AFP level, main tumor size, BCLC stage, and tumor thrombus were different among the three groups (p < 0.05)." (PMID 35664791, 2022). "The aim of this paper was to observe and describe the correlation between serum AFP level and tumour size in patients with HCC, that previously received DAAs therapy for HCV infection." (PMID 35497085, 2022). "≥76% decrease in AFP change or ≥30% decrease in tumor size of the viable target lesions, taking as reference the baseline target lesions." (PMID 35686094, 2022). "Linear regression analyses using a path diagram revealed that circulating miR-675 was a significantly higher positive predictor than tissue lncRNA-H19 to tumor size, pathologic grade, and serum AFP level." (PMID 36671388, 2022).
tumor (continued). "Levels of serum AFP, an oncofetal protein that is used as a tumor marker, significantly increased in the STAM vehicle control group and decreased in the combination treatment group." (PMID 35203369, 2022). "Blood biochemistry examination, urinalysis, and tumor markers (alpha-fetoprotein, human chorionic gonadotropin, and lactate dehydrogenase) showed no abnormal findings." (PMID 36335378, 2022). "We demonstrated that HCC patients in Vietnam were younger, and had more aggressive tumor characteristics, such as higher serum AFP level, larger size of tumor, more macrovascular invasion and more extrahepatic metastasis, compared to those in Taiwan." (PMID 36423180, 2022). "And we testify in TGCA database, we found the higher expression of SKA1-3 in tumor group, pathological stage III and IV group, tumor status and AFP more than 400ng/ml group." (PMID 36439516, 2022). "Univariate analysis showed that sex, Edmondson grade, microvascular invasion, tumor stage (III–IV/I–II), AFP, and DDX60L expression were strongly associated with the prognosis of HCC patients." (PMID 35223465, 2022). "Although alpha-fetoprotein (AFP) is commonly applied as a tumor indicator for the diagnosis of HCC, its low specificity and accuracy are its shortage, which leads to patients missing the best treatment period." (PMID 35620462, 2022). "Some other serum tumor markers, such as alpha-fetoprotein (AFP), carbohydrate antigen 125 (CA125), and carbohydrate antigen 153 (CA153) can also be elevated in CRC." (PMID 35433129, 2022). "The system divides patients into good, intermediate, and poor prognosis groups based on the primary site, pretreatment tumor marker levels (AFP and beta-human chorionic gonadotropin), serum lactate dehydrogenase (LDH) levels, and disease severity." (PMID 36016622, 2022). "Multivariate Cox regression analysis indicated that AFP, APRI, MVI, number of tumours, tumour diameter and PVTT were independent risk factors for 2-year RFS; ALT was an independent protective factor of 2-year RFS." (PMID 35255845, 2022). "A simplified score has been calculated from three US centers based on tumor size and number plus AFP response on a gradual basis (200, 400, and 1,000 ng/ml)." (PMID 35529597, 2022). "There were no significant intergroup differences with respect to age, sex, HBV infection, tumor differentiation, rate of satellite lesions, and AFP > 400 ng/mL." (PMID 35585534, 2022). "The determination of the tumour marker AFP has long been established in the screening, diagnosis and follow-up of HCC." (PMID 36233670, 2022). "Univariate Cox regression analysis identified that AFP level, tumor size, tumor number, Edmondson’s grade, vascular invasion, GPS, NLR, PLR, SII, and ACLR were associated with both OS and TTR." (PMID 35756674, 2022). "We found the expression of PCNAP1 to be at relatively high and stable levels in cancer tissue and the plasma of HCC patients, and that PCNAP1 levels correlated with alpha-fetoprotein (AFP), a clinical tumor marker of HCC." (PMID 35224110, 2022). "Age, male gender, elevated serum AFP level, tumor size, background liver, and special histopathological variants are considered key indicators for patient outcomes." (PMID 36117166, 2022). "PD-L1 overexpression on tumor cells or inflammatory cells had a considerable relationship with tumor aggressiveness, such as poor differentiation, high AFP levels, satellite nodules, and vascular invasion." (PMID 36249023, 2022). "Tumor markers such as alpha-fetoprotein (AFP), carcinoembryonic antigen (CEA), CA19–9, CA72.4, and CA125 have low sensitivity 34 (<40%), and their specificities are modest for GC patients." (PMID 35328635, 2022). "Among them, alpha-fetoprotein (AFP) is a commonly used serum tumor marker, although it has certain specificity." (PMID 35449838, 2022).